STK11 (serine/threonine kinase 11)
Diseases named in the same sentence as STK11 in open-access papers (continued):
Sharing a sentence is not in itself a finding about the gene and the disease.
tumor (continued). "Further, our results raise the intriguing possibility that YAP1 antagonism may represent a therapeutic approach to counter anti-PD-1 therapy resistance in STK11-null, KRAS-driven LUADs by modulating tumor-intrinsic gene expression to promote a “hot” tumor immune microenvironment." (PMID 37968341, 2024). "Further, we speculate YAP1 antagonism may represent a synergistic strategy to sensitize patients with KRAS-driven LUADs lacking STK11 to anti-PD-1 therapy by promoting a “hot” tumor immune microenvironment." (PMID 37968341, 2024). "The authors concluded that KRAS mutations could be associated with improved survival in NSCLC patients treated with immunotherapy in the absence of mutations in the STK11 and KEAP1 genes in tumor cells." (PMID 37509393, 2023). "Interestingly, in a preclinical study using sgRNA library screening and knockout tumor xenograft models, only the loss-of-function mutation of KEAP1 (but not STK11/LKB1) induced partial resistance to adagrasib." (PMID 37925476, 2023). "Tumor cell immunohistochemical PD-L1, plasma soluble PD-L1 (sPD-L1), TMB/blood TMB (bTMB), mismatch repair defect (dMMR)/microsatellite instability-high (MSI-H), and other biomarkers such as KRAS, STK11, KEAP1, and DNA damage response (DDR) gene variation are potential biomarkers." (PMID 36406130, 2022). "Genetic analysis of tumor samples by Next Generation Sequencing (NGS) from treatment resistant patients highlighted that several genetic alterations can contribute to therapy resistance and reduced patient survival e.g. KRAS, STK11, KEAP1 and the phosphatase and tensin homologue (PTEN)." (PMID 35477555, 2022). "Therefore, activation of STING in STK11 mutant cancer is a promising approach to convert an immune-resistant, noninflamed tumor into an immune-sensitive, inflamed tumor." (PMID 35281267, 2022). "In the Pten- and Stk11-deficient GEMM LUSC model, inhibition of neutrophil’s CXC chemokine receptors 1 and 2 (CXCR1/2)—which regulate their recruitment to the TIME110—combined with anti-PD1 treatment, decreased tumour masses, unlike single therapy treatment." (PMID 34354223, 2021). "It would have been of interest to see how the expression of STK11 differed in the context of the presence of other comutations like KEAP1 or KRAS and to analyze the tumor microenvironment, as the composition of different immune cells might be different among different KRAS mutations." (PMID 33572782, 2021). "LKB1, also named serine/threonine-protein kinase (STK11), functions as a major regulator of energy homeostasis through the activation of AMP-activated protein kinase (AMPK) and plays an important role in vascular development, cell polarity, cell growth, and tumor suppression." (PMID 33924999, 2021). "In this series, we could not test the impact of co-mutations, such as STK11/LKB1 mutations, or tumour mutational burden, potentially affecting immunotherapy sensitivity, due to the low number of samples with available data." (PMID 32376889, 2020). "Notably, this particular tumor was taken from a patient that was LKB1 (STK11) negative." (PMID 40629079, 2025). "A molecular testing panel of the tumor tissue showed the presence of 21 mutations (none of them treatable), including MDM2 (murine double minute 2), KRAS (Kirsten rat sarcoma) amplification, RB1 (retinoblastoma protein) amplification, and STK11 (serine/threonine kinase 11)." (PMID 34298855, 2021). "Germline variants not previously reported in WT were: CDKN2A R24Q (XJN) and STK11 L245F (QXN), both of which became homozygous in the tumor through LOH." (PMID 40340749, 2025).
tumor (continued). "FOXA1, STK11, TSC1 and TSC2 were found to have no concordance between tumours and were largely restricted to metastases." (PMID 32811538, 2020). "As both SFRP1 and CREB3L1 could inhibit tumor proliferation, reduced CREB3L1 expression could not inhibit CCA proliferation, we excluded CREB3L1 and STK11 from our analysis." (PMID 27385214, 2016). "Lack of STK11 expression enhances neutrophil recruitment that inhibits CD8+ T cells and increases the expression of tumor cytokines, which reduces the efficacy of CD8+ T cells in anti-tumor immunity, and eventually promotes resistance to anti-PD-1/PD-L1 inhibitor." (PMID 40296912, 2025). "Based on the analysis of the genetic alteration profile of the tumor, there were no preexisting genomic alterations in antigen processing and presentation as well as immune response, such as B2M, PTEN, STK11, which might account for de novo resistance to ICI treatment." (PMID 34898561, 2021).
cancer (736 papers, 1999 to 2026). A tumor composed of atypical neoplastic, often pleomorphic cells that invade other tissues. "Several cancer types have shown the loss of LKB1 function through somatic alterations in the STK11 gene." (PMID 40647497, 2025). "We postulate that analysis of STK11 lesions combined with known predisposing genetic variants is a feasible future prospect to improve individual cancer risk estimates and understand phenotype variability." (PMID 40860288, 2025). "In contrast, CXCL13 was negatively associated with PEBP1/STK11 co-expression in almost all cancer types." (PMID 40806276, 2025). "Mutation in the STK11 gene in A549 cells potentiates cancer hallmarks, such as deregulation of cellular metabolism, aside from the Warburg effect, mTOR activation, autophagy inhibition, and NRF2 and redox activation." (PMID 39955067, 2025). "An integrated analysis was further conducted to assess the regulatory impact of the PEBP1/STK11 co-expression signature on ten major cancer-associated pathways across diverse cancer types." (PMID 40806276, 2025). "This negative correlation indicates that the higher expression levels of PEBP1 and STK11 are associated with increased drug sensitivity across various cancer types." (PMID 40806276, 2025). "There is also some potential for cancers driven by STK11 mutations to be more sensitive to alternative therapeutics." (PMID 40791513, 2025). "Further studies are needed to aggregate genetic data and clarify the relationship between STK11 variants and cancer risk in PJS." (PMID 39895895, 2025). "RKIP and LKB1, encoded by PEBP1 and STK11, respectively, have emerged as key regulators of cancer pathophysiology." (PMID 40806276, 2025). "Among the hypoxia-related molecules, MRPS17, CDCHD2, PSMA7, and MIF consistently demonstrated a positive correlation with PEBP1/STK11 co-expression across all cancer types in which a significant association was observed." (PMID 40806276, 2025). "In the context of the diverse cancer types in which STK11 somatic variants are found, our map offers the potential to distinguish those in which STK11 is a passenger mutation as opposed to being a cause (driver) of the cancer." (PMID 40791513, 2025). "Researchers have made substantial advancements in characterizing STK11 gene mutations, elucidating the molecular mechanisms underlying cancer predisposition while also identifying complex genotype-phenotype correlations." (PMID 40989965, 2025). "Elevated MDSC accumulation has been observed in STK11-mutated PJS polyps compared to sporadic polyps, implicating an immunobiological link to cancer susceptibility following STK11 loss." (PMID 41051525, 2025). "Our result showed that the risk of death in patients with high expression of STK11 decreased by 58%, while the risk of cancer recurrence and metastasis decreased by 64%." (PMID 38736875, 2024). "Loss-of-function mutations in the STK11 gene lead to dysregulated cell growth and division, contributing to the development of polyps and increasing the risk of cancer in individuals with PJS." (PMID 38800180, 2024). "Of note, it has been reported that the STK11 mutation was involved in metabolic reprogramming of cancer cells, and metformin modulates metabolism predominantly through AXIN1-dependent activation of AMP-activated protein kinase (AMPK)." (PMID 39308524, 2024). "Mutations in the STK11 gene, also known as LKB1, represent a tumor suppressor gene implicated in the autosomal dominant disorder that predisposes individuals to cancer known as Peutz–Jeghers syndrome (PJS)." (PMID 39199653, 2024). "STK11 mutations have been identified as significant genetic events in various cancer types, notably within the context of NSCLC." (PMID 39199653, 2024).
cancer (continued). "In summary, the management of PJS requires a multifaceted approach that considers the specific genetic variants of the STK11 gene and their implications for cancer risk and clinical outcomes." (PMID 39767561, 2024). "Peutz–Jeghers syndrome (PJS) is a rare hereditary disorder linked to increased cancer risk due to specific genetic variants in the STK11 gene." (PMID 39115133, 2024). "The prognostic role of STK11 mutations in combination with co-occurring alterations in other cancer genes is being evaluated in various studies, with poor ICI outcomes observed in patients with low TMB or KRAS co-mutation." (PMID 39045411, 2024). "This is caused by alternative carcinogenic pathways induced by the genomic heterogeneity in these cancers, such as PD-L1 expression or co-mutations in STK11 and KEAP1." (PMID 37110848, 2023). "We categorized patients with KRAS G12C, KEAP1, and STK11 mutational status using both solid and liquid assays; patients with cancer that was categorized as WT were assigned based on solid assays only." (PMID 37069542, 2023). "The downregulation of varied proteins (DAPK, PTEN, TSC1, TSC2, and LKB1/STK11) is associated with lysosomal degradation capacity in cancer cells." (PMID 37527766, 2023). "Together these findings demonstrate that STK11/LKB1 genetic loss is sufficient to induce CC across multiple cancer types and different host backgrounds." (PMID 37092555, 2023). "Ultimately, the presence of STK11/LKB1 ctDNA gene variants was highly associated with cancer-associated weight loss at NSCLC diagnosis and portended the worst overall survival among all combination of cohorts." (PMID 37092555, 2023). "Validation of STK11/LKB1 variants as a biomarker for NSCLC-associated patient weight loss at cancer diagnosis." (PMID 37092555, 2023). "Other genomic alterations, like STK11/LKB1 mutation, can be important for specific cancers or can further modulate immunogenicity." (PMID 35703181, 2022). "STK11 is a cancer-suppressive gene encoding LKB1 protein that acts as a critical regulator of cellular metabolism and energy sensing by activating AMP kinase (AMPK)." (PMID 35406531, 2022). "In this study, 44 PJS patients among 35 families were detected to have 31 different STK11 germline variants that were associated with cancer." (PMID 36033506, 2022). "We collected 31 different STK11 germline variants that were associated with cancer in a total of 44 index patients and/or in relatives with PJS from 35 families, including 26 (26/31, 83.87%) point variants and five (5/31, 16.13%) genomic deletions." (PMID 36033506, 2022). "The interaction of KRAS and STK11 has also been demonstrated to have prognostic importance across cancers as coalteration of these genes is associated with overall worse prognosis." (PMID 35703181, 2022). "An intriguing finding was the overrepresentation of cancer-related point variants; 34.62% (9/26) were presented within the STK11 kinase domain XI and were all associated with digestive system malignancies." (PMID 36033506, 2022). "For the analyses of variation types, 76.92% (20/26) cancer-related STK11 germline point variants were truncating variants, which supported the possibility that truncating variants were associated with a more severe phenotype." (PMID 36033506, 2022). "Recent studies found that STK11 mutation exposed cancer cells to metabolic crisis and apoptosis, and sensitized those cells to the antidiabetic compounds, which lower intracellular ATP levels by inhibiting mitochondrial oxidative phosphorylation." (PMID 35281267, 2022). "Seven variants were novel and thus extended the spectrum of known disease-causing and cancer-related STK11 variants." (PMID 36033506, 2022).
cancer (continued). "STK11 was first identified as the cancer susceptibility locus for familial Peutz-Jeghers syndrome (PJS), which is characterized by mucocutaneous pigmentation and gastrointestinal hamartoma with an increased cancer risk." (PMID 34142658, 2021). "STK11/LKB1 loss of function has been found in several cancer types, mainly through somatic alterations in the STK11 gene such as non-sense mutation, loss of heterozygosity, insertions, intragenic deletions, or chromosomal deletions." (PMID 34831355, 2021). "The gene encoding LKB1 in humans (STK11) had been shown a few years earlier to be the primary gene mutated in Peutz–Jeghers syndrome, a hereditary predisposition to cancer." (PMID 33375416, 2020). "Mutations in STK11, the second tumor suppressor gene most frequently mutated in NSCLCs, lead to loss of LKB1 protein expression which precludes the possibility to directly targeting the cancer-associated, mutated product." (PMID 33194590, 2020). "Loss of STK11 function was found to be associated with the metastasis in various cancer types, such as lung and head–neck." (PMID 33149122, 2020). "STK11 inactivating mutations lead to Peutz–Jeghers syndrome, a condition that is characterized by gastrointestinal polyps and increased risk for cancer." (PMID 32429240, 2020). "During malignant progression, different types of cancer inhibit STK11 function by mutation or epigenetic inactivation." (PMID 32911741, 2020). "As such, individuals with pathogenic STK11 variants are recommended to receive increased cancer screening at a younger age." (PMID 31623605, 2019). "We also showed that, consistent with PTEN-SSL activity, PTEN and STK11 had mutually exclusive patterns of mutations in the MSK-IMPACT pan-cancer study." (PMID 29566768, 2018). "In this study, peripheral blood genomic DNA samples from a Chinese PJS family with a high cancer risk were examined for STK11 mutations using Sanger sequencing and MLPA analysis." (PMID 29720104, 2018). "Different cancer risks due to different STK11 mutations have been recognized through hundreds of cases reported previously, however the STK11 mutation spectrum and genotype-phenotype correlation are still poorly understood." (PMID 29141581, 2017). "In cases with wild-type KRAS, BRAF and PIK3CA a number of cancer-associated genes representing potential drivers were identified (for example, STK11, GNAS, CHEK2 and RB1)." (PMID 25855536, 2015). "Despite this, solid evidence for STK11 loss-of-function mutations has been identified in relatively few sporadic cancers." (PMID 26068970, 2015). "PJ patients are at increased risk to develop cancer particularly at body sites with higher levels of STK11 enzyme in the normal tissue." (PMID 23305393, 2013). "DNA samples of 5 cancer cases were subjected to standard PCR amplification of STK11 exons 1 to 9 and analyzed for somatic mutations by direct nucleotide sequencing analysis." (PMID 23305393, 2013). "Our study showed that the risk for cancer, gastrointestinal and breast, associated with germline LKB1/STK11 mutations is high and supports recent implementation of screening protocols suggested for patients." (PMID 12865922, 2003). "Cancers with RB1 or STK11 deficiencies show sensitivity to PARP inhibition." (PMID 41541668, 2026). "Mutations in STK11, particularly those affecting its regulatory domains, may significantly increase cancer risk in patients with PJS, and that STK11IP plays a crucial role in modulating STK11 activity." (PMID 39895895, 2025). "This suggests that restoring STK11 function or targeting its downstream effectors may offer a promising therapeutic approach for treating STK11-deficient cancers." (PMID 41051525, 2025). "Variants in STK11 exons have been associated with differing cancer risks." (PMID 39895895, 2025).